SGCD (sarcoglycan delta)
Description:
Component of the sarcoglycan complex, a subcomplex of the dystrophin-glycoprotein complex which forms a link between the F-actin cytoskeleton and the extracellular matrix.
Synonyms: 35DAG; DAGD; LGMD2F; CMD1L; LGMDR6; SG-delta; SGCDP; SGD
Tractability: Antibody: its Gene Ontology location is reachable by antibodies, with high confidence; UniProt places it where antibodies can reach, with medium confidence; UniProt predicts a signal peptide or a membrane-spanning region. PROTAC: its protein half-life has been measured.
Gene: Protein-coding gene on chromosome 5 (155,870,344 to 156,767,788, forward strand). Ensembl gene ENSG00000170624.
Subcellular location: Cell membrane, sarcolemma; Cytoplasm, cytoskeleton
Pathways (Reactome):
Extracellular matrix organization: Formation of the dystrophin-glycoprotein complex (DGC)
Gene Ontology:
Biological process: camera-type eye development; cardiac muscle tissue development; heart contraction; muscle organ development
Cellular component: dystrophin-associated glycoprotein complex; endoplasmic reticulum membrane; Golgi membrane; neuromuscular junction; plasma membrane; sarcoglycan complex; sarcolemma; cytoskeleton; dystroglycan complex; membrane; sarcoplasmic reticulum
Genetic constraint (gnomAD): Loss-of-function variants: 9 observed, 17.84 expected, observed/expected ratio (o/e) 0.5, 90% interval 0.3 to 0.88. The upper end of that interval is the gene's LOEUF score, 0.88, which puts it in group 3 of 6, group 1 being the genes least tolerant of losing a copy. Missense variants: 218 observed, 213.59 expected, observed/expected ratio (o/e) 1.02, 90% interval 0.91 to 1.14. Synonymous variants: 85 observed, 81.97 expected, observed/expected ratio (o/e) 1.04, 90% interval 0.87 to 1.24.
Gene-disease validity (ClinGen):
ClinGen rates the evidence that SGCD causes each of these diseases.
autosomal recessive limb-girdle muscular dystrophy (autosomal recessive): Definitive. Autosomal recessive form of limb-girdle muscular dystrophy.
dilated cardiomyopathy 1L (autosomal dominant): Limited. Any familial isolated dilated cardiomyopathy in which the cause of the disease is a mutation in the SGCD gene.
Homologues: Orthologues: chimpanzee SGCD (100% identical), macaque SGCD (99% identical), dog SGCD (98% identical), rabbit SGCD (97% identical), guinea pig SGCD (97% identical), pig SGCD (97% identical), rat Sgcd (94% identical), mouse Sgcd (94% identical), tropical clawed frog sgcd (79% identical), zebrafish sgcd (72% identical), Drosophila melanogaster Scgdelta (37% identical), Caenorhabditis elegans sgn-1 (35% identical). Paralogues in human: SGCZ (58% identical), SGCG (52% identical).
Diseases named in the same sentence as SGCD in open-access papers:
SGCD is named in the same sentence as 47 diseases in open-access papers, as found by Europe PMC text mining. Sharing a sentence is not in itself a finding about the gene and the disease. The quoted sentences say what the papers report.
cardiomyopathy (14 papers, 2009 to 2026). A disease of the heart muscle or myocardium proper. "Alterations in sarcolemma proteins such as delta-sarcoglycan (SGCD), a member of the dystrophin-associated protein complex, also increase myofilament Ca2+ sensitivity, leading to diastolic dysfunction and cardiomyopathy." (PMID 39355352, 2024). "Particularly, the recent study confirmed that the c.S151A mutation in SGCD causes a mild, subclinical cardiomyopathy phenotype." (PMID 28412737, 2017). "SGCD complex, which is involved in proper muscular functioning, has been associated with the limb-girdle muscular dystrophy and cardiomyopathy." (PMID 20830292, 2010). "Loss of SGCD function leads to muscle dysfunction and may progress to cardiomyopathy characterized by localized fibrosis." (PMID 40805113, 2025). "Eight (11.59%) hits concerned substrate defects, such as fibro-adipose substitution or RV end-diastolic volume (EDV), and they mainly involved genes associated with cardiomyopathies and muscle dysfunction, including TRIM63, MYH6, SGCD and LAMA2." (PMID 36008935, 2022). "Those authors identified genes implicated in cardiac calcium homeostasis (PDE3B), oxidative stress response (FDXR and SPATA18), and the etiology of cardiomyopathy (SGCD, BBC3 and GDF15)." (PMID 33820914, 2021). "SGCD-null mice, likewise develop cardiomyopathy with focal areas of fibrosis due to abnormalities in the coronary vasculature." (PMID 28797108, 2017). "Sarcoglycan delta (SGCD) encodes a crucial component of the dystrophin-glycoprotein complex, and variants in this gene have been implicated in both muscular dystrophies and cardiomyopathies." (PMID 41840602, 2026). "Another gene of interest may be SGCD, which is involved in cardiomyopathy and age-related macular degeneration, and provided a large majority of SNP-level nominally significant hits, but remained unassociated previously with MO." (PMID 40350427, 2025). "Cardiomyopathy is not a core component of sarcoglycanopathies, still there have been reports of several patients without cardiac involvement and mutations in the SGCD gene have also been reported to cause autosomal-dominant dilated cardiomyopathy (DCM) independently from LGMD phenotypes." (PMID 30733730, 2018). "Therefore, by measuring collagen type I positive areas in heart we studied whether SGCD-null mice develop cardiomyopathy." (PMID 28797108, 2017). "Mutations of SGCD cause LGMD2F, and although clinical presentation is largely similar among the four sarcoglycanopathies, this is the only subtype not consistently characterized by concomitant cardiomyopathy." (PMID 28697784, 2017).
muscular dystrophy (13 papers, 2008 to 2026). Muscular dystrophy (MD) refers to a group of more than 30 genetic diseases characterized by progressive weakness and degeneration of the skeletal muscles that control movement. "Based on current knowledge of gene function in other mammalian species, including humans, hamsters, and dogs, we propose the SGCD missense variant as the causative variant of the observed form of muscular dystrophy in the index case." (PMID 37628692, 2023). "Based on current knowledge of gene function in other mammalian species, we propose the SGCD missense variant as the most likely causative variant for the observed form of muscular dystrophy in the presented dog." (PMID 37628692, 2023). "We prioritized a single homozygous private protein-changing variant in exon 8 of the SGCD gene, a known candidate gene for recessively inherited forms of muscular dystrophy (OMIM 601287)." (PMID 37628692, 2023). "Another gene fusion involved the SGCD (Sarcoglycan Delta) and DNAH11 (Dynein Axonemal Heavy Chain 11) genes; SGCD is associated with muscular dystrophy, which could determine vascular malformations." (PMID 40904803, 2025). "The other validated fusion involves sarcoglycan delta (SGCD), a gene known to cause muscular dystrophy in mammals when deleted or mutated, an event that could lead to vascular malformations as reported in the GS lesions." (PMID 35668402, 2022). "Mutations of SGCD were accompanied with dilated cardiomyopathy and muscular dystrophy in Caucasians, although not previously reported on TAPVR." (PMID 28412737, 2017). "An automated process has been developed for the detection of deletions, duplications/insertions and point mutations in any gene or family of genes and has been applied to ten genes known to bear mutations that cause muscular dystrophy: DMD; CAV3; CAPN3; FKRP; TRIM32; LMNA; SGCA; SGCB; SGCG; SGCD." (PMID 19835634, 2009). "Also, there were no CNVs detected in the targeted analysis of SGCA, SGCB, SGCG, SGCD, and FKRP genes for other frequent limb-girdle muscular dystrophies." (PMID 36425804, 2022).
Sarcoglycanopathies (12 papers, 2017 to 2025). "Sarcoglycanopathies (SGPs) are autosomal recessive limb-girdle muscular dystrophies (LGMDs) caused by mutations in four genes: SGCA, SGCB, SGCG, and SGCD, which lead to α-SGP (LGMDR3), β-SGP (LGMDR4), γ-SGP (LGMDR5), and δ-SGP (LGMDR6), respectively." (PMID 39755676, 2025). "Sarcoglycanopathies are caused by mutations in the SGCA, SGCB, SGCG, and SGCD genes that code for α-, β-, γ-, and δ-sarcoglycan (SG), respectively." (PMID 41009401, 2025). "Sarcoglycanopathies (SGPs) are limb-girdle muscular dystrophies (LGMDs) that can be classified into four types, LGMDR3, LGMDR4, LGMDR5, and LGMDR6, caused by mutations in the genes, SGCA, SGCB, SGCG, and SGCD, respectively." (PMID 39755676, 2025). "Sarcoglycanopathies are caused by mutations which occur in LGMD genes SGCA, SGCB, SGCG, and SGCD that lead to misfolding, truncated, or loss of protein of α, β, γ, and δ protein which stabilizes the sarcolemma of muscle cells." (PMID 40225150, 2023). "Sarcoglycanopathies (R3-R6) are caused by missense mutations of SGCA, SGCB, SGCG, and SGCD genes, that result in misfolding of the four corresponding sarcoglycan protein subunits that form the sarcoglycan complex in the sarcolemma of muscle cells." (PMID 34110586, 2021). "Sarcoglycanopathies are caused by mutations, mostly missense, in the SGCA, SGCB, SGCG, and SGCD genes." (PMID 34110586, 2021). "SGCD mutations causing LGMD2F and its clinical presentation are largely similar among the four sarcoglycanopathies." (PMID 30733730, 2018). "Among them are sarcoglycanopathies caused by mutations in at least four genes named SGCA, SGCB, SGCG and SGCD." (PMID 28883879, 2017). "Delta-sarcoglycanopathy (LGMDR6/LGMD2F) is caused by recessive mutations in the SGCD gene and was originally described in 1996,9–11 and is thought to be the least common type of sarcoglycanopathy although the number of existing cases is not known." (PMID 34515763, 2022). "Sarcoglycanopathies include four subtypes of autosomal recessive limb-girdle muscular dystrophies (LGMDR3, LGMDR4, LGMDR5 and LGMDR6) that are caused, respectively, by mutations in the SGCA, SGCB, SGCG and SGCD genes." (PMID 34515763, 2022). "Sarcoglycanopathies comprise four subtypes of autosomal recessive limb-girdle muscular dystrophy (LGMD2C, LGMD2D, LGMD2E, and LGMD2F) that are caused, respectively, by mutations in the SGCG, SGCA, SGCB, and SGCD genes." (PMID 30764848, 2019). "Sarcoglycanopathies (SG) are the most frequent form of autosomal recessive LGMD comprising of four subtypes, LGMDR3, LGMDR4, LGMDR5, and LGMDR6, caused by mutations in SGCA, SGCB, SGCG, and SGCD encoding for the alpha-, beta-, delta-, and gamma-sarcoglycan proteins, respectively." (PMID 40225150, 2023). "The sarcoglycanopathies are a severe form of limb girdle muscular dystrophy caused by mutations in the sarcoglycan genes SGCA, SGCB, SGCG, and SGCD, leading to reduced or absent expression of the alpha-, beta-, gamma-, and delta-sarcoglycan proteins respectively." (PMID 40129306, 2025).
dilated cardiomyopathy (10 papers, 2014 to 2024). Cardiomyopathy which is characterized by dilation and contractile dysfunction of the left and right ventricles. "SGCD, a gene highly expressed in skeletal and cardiac muscles associated with dilated cardiomyopathy, is involved in the Ca2+ signaling, which directly influences apoptosis induction in tumor cells." (PMID 39376659, 2024). "SGCD mutations are associated with autosomal recessive limb-girdle muscular dystrophy and dilated cardiomyopathy." (PMID 35990266, 2022). "Mutations in the SGCD gene are associated with limb-girdle muscular dystrophy and dilated cardiomyopathy." (PMID 25474115, 2014). "SGCD gene sarcoglycan delta may contribute to the embryonic heart response in animals and is associated with autosomal recessive limb-girdle muscular dystrophy and dilated cardiomyopathy due to SGCD mutations." (PMID 38778305, 2024). "Carriers of the Arg71Thr mutation in the SGCD gene have a late onset of dilated cardiomyopathy." (PMID 37662558, 2023). "Dilated cardiomyopathy is a condition in which the heart becomes enlarged and cannot pump blood efficiently; a small number of individuals who develop dilated cardiomyopathy without skeletal muscle involvement have a mutation in one copy of the SGCD gene in each cell." (PMID 25474115, 2014). "Finally, two more proteins were found to be upregulated upon treatment: sarcoglycan delta (SGCD) and serum response factor binding protein 1 (SRFBP1), usually downregulated or mutated in hypertrophic and dilated cardiomyopathies and during heart failure, respectively." (PMID 32121252, 2020). "The dilated cardiomyopathy (DCM) pathway involves proteins such as Desmin, DMD, Titin, Tnt, ACTA1, TPM, Laminac, SGCD, TNF-α, IGF-1, TGF-β, and Ang-II." (PMID 32419790, 2020).
limb-girdle muscular dystrophy (6 papers, 2010 to 2025). Limb-girdle muscular dystrophy (LGMD) is a heterogeneous group of muscular dystrophies characterized by proximal weakness affecting the pelvic and shoulder girdles. "Our results, combined with current knowledge of SGCD function in other species, provide strong evidence for an extremely rare missense variant affecting a conserved residue of SGCD as the most likely causative genetic variant for recessive limb-girdle muscular dystrophy in the Lagotto Romagnolo dog." (PMID 37628692, 2023). "For these individuals, mutation analysis was extended to include the seven most common limb-girdle muscular dystrophy (LGMD) genes (DYSF, CAPN3, SGCA, SGCB, SGCC, SGCD, and FKRP)." (PMID 31588416, 2017).
Duchenne muscular dystrophy (3 papers, 2013 to 2020). Duchenne muscular dystrophy (DMD) is a neuromuscular disease characterized by rapidly progressive muscle weakness and wasting due to degeneration of skeletal, smooth and cardiac muscle. "Exon 2, which harbors the start codon and transmembrane intracellular domains of SGCD, is targeted in a genetically modified mouse Duchenne muscular dystrophy (DMD) model." (PMID 32060408, 2020).
retinal degeneration (2 papers, 2018 to 2019). Degeneration of the retina. "Furthermore, in a manuscript in preparation we have evidenced that the deficient SGCD-null mice exhibited signs of retinal degeneration and frailty, highlighting the pivotal role of SGCD for the normal retinal function." (PMID 30257524, 2018).
benign breast disease (1 paper, 2017). "In two of these genes, α1-syntrophin (SNTA1, that forms a complex with SNTG1) and δ-sarcoglycan (SGCD), there is evidence of decreased protein expression in benign breast disease." (PMID 29290962, 2017).
dilated cardiomyopathy 1L (1 paper, 2009). "Defects in SGCD are the cause of limb-girdle muscular dystrophy type 2F (LGMD2F) and dilated cardiomyopathy 1L (CMD1L)." (PMID 19412524, 2009).
fibrosis (1 paper, 2017). the formation of excess fibrous connective tissue in an organ or tissue in a reparative or reactive process. "Cardiac fibrosis was found in SGCD-null mice, being more severe in males than in females." (PMID 28797108, 2017).
Hyperglycemia (1 paper, 2020). An increased concentration of glucose in the blood. "Based on human GWAS, SGCD, which is a component of the sarcoglycan complex, and JADE2, which acts as an E3 ubiquitin ligase, were suggested as candidate genes for impaired insulin secretion and hyperglycemia in the R2 congenic region (segment B)." (PMID 32703163, 2020).
Insulin resistance (1 paper, 2011). Increased resistance towards insulin, that is, diminished effectiveness of insulin in reducing blood glucose levels. "In future it has to be validated if the other most differentially regulated genes between both tissues such as: SGCD, LCE3D, EREG, NDP and CXCL9, FSTL3, PDZK1IP1 could be used as biomarkers related to insulin resistance of adipose or liver tissues respectively." (PMID 21978410, 2011).
knee osteoarthritis (1 paper, 2024). "Specifically, cinnamaldehyde may affect knee osteoarthritis by regulating apoptosis-related genes such as ZFAND5, BCL6, ELL2, FOSL2, MARCKS, and SGCD." (PMID 39376659, 2024).
osteoarthritis (1 paper, 2024). A noninflammatory degenerative joint disease occurring chiefly in older persons, characterized by degeneration of the articular cartilage, hypertrophy of bone at the margins and changes in the synovial membrane. "Firstly, the identified APDEGs—MARCKS, ZFAND5, BCL6, FOSL2, ELL2, and SGCD—may provide deeper insights into osteoarthritis pathogenesis." (PMID 39376659, 2024).
cancer (6 papers, 2014 to 2025). A tumor composed of atypical neoplastic, often pleomorphic cells that invade other tissues. "However, few studies regarding the gene SGCD, a component of the sarcoglycan complex in cancer biology, have been previously reported." (PMID 35789544, 2023).
tumor (6 papers, 2017 to 2026). "By this interpretation, the most decreased expression in tumor protein relative to healthy tissue is in ROBO1 ∼72.3%, followed by delta sarcoglycan (encoded by SGCD) ∼68.9%, and syntrophin gamma 1 (SNTG1 gene) ∼58% (SGCD)." (PMID 29290962, 2017). "Taken together, it is conceivable that the EV PPP1R12A may reflect the effect of PDAC cells whereas SCN7A and SGCD may represent essential components from the tumour microenvironment, i.e., immune cells, fibroblasts and Schwann cells." (PMID 36737824, 2023). "Regarding the expression of luminal and basal biomarkers, Layer3.1 tumor presented higher expression of KRT20, a luminal-papillary biomarker, whereas Layer3.2 had higher expression of KRT5, KRT6a, KRT14, and CD44 basal biomarkers, but also PGM5, DES, and SGCD luminal-infiltrated biomarkers." (PMID 41516353, 2026).
cardiovascular disease (1 paper, 2016). "The eight significant SNPs identified in Model 1 are located in five genes —LRP8, CAPN13, MITF, SGCD and MLL3—previously implicated in BP variation or cardiovascular disease." (PMID 28002425, 2016).
SGCD also shares sentences with these, for which no sentence is quoted: autosomal recessive limb-girdle muscular dystrophy (5 papers); Obesity (3); infection (2); age-related macular degeneration (1); autosomal dominant dilated cardiomyopathy (1); breast carcinoma (1); cardiac disease (1); congenital muscular dystrophy (1); congenital myopathy (1); delta sarcoglycanopathy (1); dermatomyositis (1); duodenitis (1); dysferlinopathies (1); dystrophinopathy (1); endometriosis (1); familial atrial fibrillation (1); Fukuyama-type congenital muscular dystrophy (1); gastric carcinoma (1); gastritis (1); geographic atrophy (1); heart failure (1); hereditary cardiomyopathies (1); hypertrichotic osteochondrodysplasia (1); hypertrophic cardiomyopathy (1); left ventricular hypertrophy (1); limb-girdle muscular dystrophy type 2F (1); muscular disorders (1); Pompe disease (1); prostate carcinoma (1); vascular malformation (1).